KILH (KRT19 interacting long noncoding RNA in hepatocellular carcinoma)
Synonyms: linc-KILH; lnc-GCLC-1
Gene: Long non-coding RNA gene on chromosome 6 (53,561,289 to 53,617,171, reverse strand). Ensembl gene ENSG00000231683.
Diseases named in the same sentence as KILH in open-access papers:
KILH is named in the same sentence as 3 diseases in open-access papers, as found by Europe PMC text mining. Sharing a sentence is not in itself a finding about the gene and the disease. The quoted sentences say what the papers report.
hepatocellular carcinoma (2 papers, 2021 to 2024). A malignant tumor that arises from hepatocytes. "Therefore, we named it as KRT19 interacting long noncoding RNA in hepatocellular carcinoma (Linc-KILH)." (PMID 33767587, 2021). "As a consequence, Linc-KILH enhanced the malignant phenotypes of hepatoma cells." (PMID 33767587, 2021).
cancer (1 paper, 2021). A tumor composed of atypical neoplastic, often pleomorphic cells that invade other tissues. "In vitro and in vivo functional experiments in Huh7, MHCC-97H and Hep3B cells revealed that the cancer promoting function of Linc-KILH on HCC cells was dependent on KRT19 expression." (PMID 33767587, 2021). "Collectively, these data further demonstrated that the cancer promoting function of Linc-KILH was dependent on the presence of KRT19 in HCC cells." (PMID 33767587, 2021).
tumor (1 paper, 2021). "We demonstrated Linc-KILH was significantly upregulated in HCC tissues compared with the corresponding non-tumor tissues in our study cohort." (PMID 33767587, 2021). "Correlation analysis revealed that high Linc-KILH expression was positively correlated with advanced tumor progression and poorer prognosis of HCC patients." (PMID 33767587, 2021).